IL1B (interleukin 1 beta)
Diseases named in the same sentence as IL1B in open-access papers (continued):
Sharing a sentence is not in itself a finding about the gene and the disease.
Encephalopathy (32 papers, 2014 to 2025). Encephalopathy is a term that means brain disease, damage, or malfunction. "Using a mouse model of inflammation‐induced encephalopathy of prematurity driven by systemic administration of pro‐inflammatory IL‐1β, we sought to uncover causes of cerebellar damage." (PMID 35579329, 2022). "Increased IL-1β expression has been detected in the cerebrospinal fluid of term neonates with encephalopathy and was strongly associated with impaired neurodevelopmental outcomes." (PMID 34465372, 2021). "In fact, SIRT1 activation by Resveratrol prevented NLRP3 expression and IL-1β cleavage in hippocampus of mice with sepsis-associated encephalopathy." (PMID 31327964, 2019). "Attention is drawn to the curious phenomenon of the same encephalopathies being often defined only in TNF or IL‐1β terms." (PMID 35174650, 2022). "Previous studies reported increased serum and cerebrospinal fluid concentrations of IL-1β, IL-6, IL-10, and TNF-α, as well as increased transcription of their coding genes in patients with influenza-associated encephalopathy and FS." (PMID 34300253, 2021). "The early reduction in IL-1β may be particularly important and may play a neuroprotective function in the development of encephalopathy and may counteract the initial inflammatory response of other cytokines." (PMID 35955430, 2022). "The findings suggested that inflammatory factors, such as IL‐1β, IL‐18 and TNF‐α, play an important role in the pathogenesis of encephalopathies." (PMID 38683122, 2024). "The systemic administration of Ig following HI encephalopathy significantly reduced the TNF-α, IL-6 and IL-1β mRNA expression levels in the ischemic tissue in the Ig + hypoxia group compared with those in the hypoxia group." (PMID 24520277, 2014). "Previous literatures have revealed that IL-6 and IL-1β showed significant correlations with PHES score and correlate with health-related quality of life irrespective of MHE Serum IL-6 and IL-18 levels are reported to be correlated with the degree of encephalopathy." (PMID 26039496, 2015).
insomnia (32 papers, 2015 to 2025). A sleep disorder characterized by difficulty in falling asleep and/or remaining asleep. "Lower gut microbiome diversity and richness and higher IL-1β levels are associated with insomnia." (PMID 35783298, 2022). "IL-1β and IL-6, common pro-inflammatory cytokines, were elevated under hypoxia and oxidative stress conditions, leading to insomnia and circadian rhythm disturbances." (PMID 40507808, 2025). "Previous studies have demonstrated that insomnia patients exhibit elevated levels of IL-6, IL-10, IL-1β, TNF-α, CRP, and other inflammatory markers." (PMID 40636389, 2025). "The relationship between IL-1β and Athens Insomnia Scale controlling for sex, age, and chronic disease, is still significant (r = 0.260; p = 0.033)." (PMID 37873780, 2023). "In our analysis, university students with more symptoms of insomnia showed higher levels of IL-1β in saliva." (PMID 37873780, 2023). "Patients with acute and chronic insomnia have increased inflammatory cytokines compared to healthy subjects, and insomnia-related signature bacteria showed a correlation with plasma interleukin (IL)-1β." (PMID 36190400, 2022). "Similar to our study, it has also been found that the levels of IL-1β in insomnia were significantly increased compared to healthy subjects." (PMID 36190400, 2022). "The analysis and figure indicate that for those with lower levels of IL-1β at baseline exercise resulted in lower insomnia scores throughout the 12-week study." (PMID 26241349, 2015). "These WM abnormalities and IL-1β levels correlated with insomnia scores." (PMID 41465566, 2025). "This study will focus on key serum biochemical markers, including neurotransmitters (5-HT and GABA), inflammatory cytokines (IL-1β, IL-6, TNF-α), and endocrine hormones (melatonin and hormones related to the HPA axis), as these have been implicated in the pathophysiology of insomnia." (PMID 40371071, 2025). "Moreover, we found that IL-1β levels were significantly higher in insomnia patients while TNF-α was significantly reduced." (PMID 36190400, 2022). "Later work revealed that PA-induced reductions in hypersomnia were positively correlated with reductions in BDNF and IL-1β, a trend that was not present in those with insomnia, suggesting differential biomarker associations for hypersomnia and insomnia." (PMID 28529805, 2017). "Furthermore, low baseline levels of IL-1β were predictive of greater reductions in insomnia during the 12-week trial." (PMID 26241349, 2015). "The results from the PPI analysis show that the targets of VVO for the treatment of insomnia mainly involve MAOB, DRD2, MAOA, IL1B, PTGS2, HTR2A, SLC6A4, and ESR1." (PMID 40004189, 2025). "Our experimental results align with previous studies, concentrations of IL-1β and TNF-α showed marked elevation in insomnia-model rodents compared to healthy controls." (PMID 41409981, 2025). "This led to elevated levels of inflammatory cytokines such as IL-1β and IL-6, activating the HPA axis and increasing the secretion of CRH, ACTH, and CORT, ultimately triggering insomnia." (PMID 40507808, 2025). "In an animal model of insomnia rats, acupuncture was found to stimulate the production of IL-1β and TNF-α while maintaining cytokine balance, thus bolstering the immune system and ameliorating insomnia symptoms." (PMID 40371085, 2025). "Both preclinical and clinical investigations have consistently observed elevated peripheral blood levels of IL-6, IL-1β, and TNF-α in insomnia patients." (PMID 41310834, 2025). "One viewpoint suggests that elevated levels of pro-inflammatory cytokines can worsen insomnia, while exercise can help restore a stable sleep–wake cycle by improving TNF-α, IL-1β, IL-6, and other pro-inflammatory cytokines." (PMID 40115345, 2025). "IL-6, IL-1β, and TNF-α are common inflammatory factors, and significantly higher IL-6 and TNF-α levels are reported in patients with insomnia than in healthy individuals, whereas decreasing their levels had a calming effect." (PMID 37670944, 2023).
insomnia (continued). "A number of cytokines and chemokines, including interleukin-1 beta (IL-1β), tumor necrosis factor-alpha (TNF-α) and IL-6, as well as high-sensitivity C-reactive protein (hs-CRP) have been shown to be related to insomnia." (PMID 28060925, 2017).
lymphopenia (32 papers, 2014 to 2025). Reduction in the number of lymphocytes. "The study results revealed that the patient group with the IL-1β gene T allele had greater WBCs counts (p = 0.040), severe lymphopenia (p = 0.007), and needed a significantly longer period on mechanical ventilators (p = 0.049)." (PMID 39452786, 2024). "Those levels also positively correlated with lymphopenia and the pro-inflammatory factors interleukin1β (IL1β), IL6, and C-reactive protein, markers associated with the anti-viral inflammatory response." (PMID 38313435, 2023). "Moreover, we further observed that lymphopenia was associated with a lower level of IL-1β and a higher level of IL-6 in diseases with poor outcomes, potentially via a direct effect of cytokines on T-cell exhaustion." (PMID 37035158, 2023). "On the other hand, lymphopenia observed in the infected hamsters strongly correlated with the increased levels of IL-1β, IFN-γ, CXCL10, and CCL2, indicating a dysregulation of T-helper-1 (Th1) cell function." (PMID 36618412, 2022). "In vitro, cortisol reduces mRNA levels of IL-1β, TNF-α, and IL-8, as well as IL-2 serum levels, causing lymphopenia during acute stress." (PMID 36425123, 2022). "The increase in IL-1β levels was accompanied by the simultaneous severe lymphopenia on the first day after laser-driven UPEB exposure, and the decreased levels occurred after the beginning of the recovery of the lymphoid population." (PMID 34768958, 2021). "Despite a large reduction in systemic toxicity, CD8α ALN-1 triggered lymphopenia in peripheral blood, comparable to WT IL-1β delivery." (PMID 32714571, 2020). "Currently, we identified a relative heterophilia, relative lymphopenia, increased HL ratio, and robust IL1β relative mRNA transcription as useful in detection of the chelonian immune response to FV3 infection." (PMID 33119713, 2020). "Furthermore, epidermal IL-1β released from damaged tissues is also a potent T-cell chemoattractant; thus, it is suspected that burn wound IL-1β may affect sequestration of T cells near the burn wound, resulting in T cell lymphopenia." (PMID 35054900, 2022). "Moreover, lymphopenia and thrombocytopenia were observed at the later stages of disease together with sharp increases in plasma levels of proinflammatory cytokines (IL-1β, IL-18, IL-6, and IFNα) and chemokines (I-TAC, MCP-1, and eotaxin), also characteristic of EHF." (PMID 28852031, 2017). "According to our data, we registered increased plasma levels of IL-1β, which occurred on the first day after laser-driven UPEB exposure, preceding the increase in lymphocyte levels after lymphopenia, and probably stimulating this growth." (PMID 34768958, 2021). "Although lymphopenia was detected in chickens from all AIV-infected groups, also 48 h pi those animals challenged with NS-reassortant viruses showed an increase of peripheral monocyte/macrophage-like cells expressing high levels of IL-1β, as determined by flow cytometry." (PMID 24460592, 2014). "Profiles of single-cell RNAseq from patient blood samples confirm the suppression of B- and T-cells (lymphopenia), T-cell exhaustion, and TNF/IL1β–driven inflammation signature not typical to all mortalities in this study." (PMID 34335605, 2021). "Interestingly, the elevated IL-10 in the serum was correlated with the appearance of lymphopenia during FMDV infection but not IL-6, IL-2, IL-17, IL-18, IL-1β, TNF-α, IFN-α/β, TGF-β, and CXCL1." (PMID 34960627, 2021).
knee osteoarthritis (31 papers, 2013 to 2025). "Various research findings have indicated that the level of IL-1β in synovial fluid in patients with knee osteoarthritis is significantly elevated." (PMID 40493319, 2025). "Knee osteoarthritis is characterized as an inflammatory osteoarticular condition, with interleukin-1β (IL-1β) and TNF-α recognized as key inflammatory mediators in its pathogenesis." (PMID 41163114, 2025). "PRP treatment for knee osteoarthritis effectively lowers the concentrations of inflammatory factors IL-6, IL-1β, TNF α, IL-17A, and IL-10, significantly alleviating knee joint pain and enhancing joint functionality." (PMID 37869166, 2023). "This is consistent with the results of 10.6 μm laser moxibustion on IL6, TNFα and IL1β in knee osteoarthritis animal models." (PMID 37593350, 2023). "As a result, the findings suggest that combining flurbiprofen perioperatively with arthroscopic debridement in individuals with knee osteoarthritis is helpful, especially for reducing the expression of IL-1β, TNF-α, COX-2, and other inflammatory factors." (PMID 35813424, 2022). "Nevertheless, in one recent study, acupuncture has been found to reduce the serum concentration of IL-1β in patients suffering from knee osteoarthritis." (PMID 35301577, 2022). "Chen found that thunder-fire moxibustion effectively reduced the contents of TNF-α and IL-1β in serum in the rat model of knee osteoarthritis, thereby inhibiting inflammatory response and alleviating symptoms." (PMID 32148545, 2020). "The objective is to investigate the clinical benefits of fire acupuncture and warming therapy for managing knee osteoarthritis of the cold-dampness subtype, while also examining the treatment’s effects on interleukin-1β (IL-1β) and matrix metalloproteinase-3 (MMP-3) in the serum." (PMID 40493319, 2025). "In rats with knee osteoarthritis, FAHFAs levels are related to IL-1β expression." (PMID 35432359, 2022). "We hypothesized that CTX‐II and IL‐1β can be used as markers for the early diagnosis and treatment of knee osteoarthritis (KOA)." (PMID 31840428, 2020). "For example, electroacupuncture relieves pain in patients with knee osteoarthritis, partly by reducing pro-inflammatory factors tumor necrosis factor-alpha (TNF-α) and Interleukin 1 beta (IL-1β)." (PMID 36337711, 2022). "We showed previously that adjunct resveratrol supplementation with NSAID reduces pain and inflammation reflected as a significant reduction of serum levels of the proinflammatory markers including IL-6, IL-1β, and TNF-α in patients with knee osteoarthritis." (PMID 34805399, 2021). "However, in a study of patients with knee osteoarthritis, a reduction in pro-inflammatory molecules (MMP-2, IL-1B, IL-6, and IL-8) and an increase in anti-inflammatory molecules (IGF-1 and IL-10) were found at the 1-year follow-up after an SVF injection." (PMID 38391657, 2024). "The present data suggest that STM attenuated chondrocyte injury induced by IL-1β by regulating ferroptosis via down-regulation of SREBF2, and may have potential as a novel therapeutic method for knee osteoarthritis." (PMID 34806937, 2021). "Similarly, we previously observed significant associations between the endo-EV and exo-EV concentrations of TNF-α, IL-6, and IFN-γ in plasma of patients with knee osteoarthritis, but not IL-1β." (PMID 38633262, 2024).
nephritis (31 papers, 2007 to 2025). Inflammation of renal tissue. "This suggests that, perhaps, loss of the repressive effects of IL-1β nudges the type I IFN-dependent nephritis even further." (PMID 37261358, 2023). "Indeed, IL-1R1– or IL-1β–deficient mice are protected from anti-GBM IgG-mediated nephritis." (PMID 32541026, 2020). "Another study found that miR-128-3p increased the expression of inflammatory cytokines such as TNF-α, IL-1β, and IL-6, whereas IL-1β is a key cytokine in kidney inflammation." (PMID 41440335, 2025). "The mRNA expressions of TNF-α and IL-1β increased significantly, which continuously activated the NF-κB signaling pathway, potentially leading to kidney inflammation." (PMID 40451077, 2025). "A recent study on lupus nephritis revealed that FcγRIIB conducted inhibitory effect on IL-1β production, which was elevated in several nephritis, in kidney macrophages through Syk signaling pathways." (PMID 38658966, 2024). "An increasing amount of evidence indicates that high urate level directly activates the NLRP3 inflammasome and subsequently promotes IL-1β maturation and secretion, contributing to kidney inflammation and renal dysfunction." (PMID 33959014, 2021). "The double staining of ED-1-positive macrophages and IL-1β indicated that glomerular staining of IL-1β was macrophage-dependent, and the double staining was abolished, along with macrophage reduction, after hMSC treatment in nephritis." (PMID 23826305, 2013). "Previous studies reported that the inhibition of IL-1β by human recombinant IL-1 receptor antagonist Anakinra or antimurine IL-1β IgG could protect kidney inflammation and fibrosis; however, the mechanism is mainly limited to one type of cell." (PMID 38615014, 2024). "Thus, heme also seems to be a potentially dangerous activator of the NLRP3 inflammasome, which actually plays a key role in IL-1β secretion during experimental kidney inflammation." (PMID 31346322, 2019). "Direct evidence comes from LPS-enhanced heterologous anti-GBM nephritis in rats which were found to be partially protected by anti-IL-1β antibody treatment, but a contribution of NLRP3, ASC, and caspase-1 for intrinsic glomerular inflammation is still speculative." (PMID 22046355, 2011). "IL-1β, a pro-inflammatory mediator known to have systemic consequences, is a marker of NLRP3 inflammasome activation and can promote kidney inflammation." (PMID 34680443, 2021). "Furthermore, this hub was associated with multiple clinical parameters, including Scr (a well-established indicator of kidney function) and IL-1β (a central element of kidney inflammation), which suggest that the response of the genus may contribute to host clinical outcomes." (PMID 32435197, 2020). "It has been shown that proinflammatory cytokines Interleukin-1 Beta (IL-1β) and tumor necrosis factor-α (TNF-α) contribute to the progression of nephritis in animal models and patients." (PMID 29643988, 2018). "In summary, heterologous anti-GBM nephritis develops independently of the NLRP3-ASC-caspase-1 axis likely due to an inability for glomerular cells to induce and to secrete IL-1β." (PMID 22046355, 2011). "In our model of mercury-induced nephritis, the levels of TNF-α and IL1-β cytokines as well as the expression of VCAM-1 molecule were significantly increased at day 13 of the disease in comparison with the controls." (PMID 17250768, 2007). "IL-1β, either directly or through the induction of other cytokines such as IL-6 and TNF-α, promotes the development of kidney inflammation by increasing the expression of adhesion molecules and chemotactic factors and by recruiting inflammatory cells, thereby inducing kidney injury." (PMID 39117988, 2025). "This study has demonstrated that high-dose CS-DMY-NPs significantly regulated the release of IL-1β, TNF-α, and IL-6 in the kidneys of mice, suggesting that DMY may attenuate LPS-induced acute kidney inflammation injury." (PMID 39330225, 2024).
nephritis (continued). "Along with increased renal expression of Il1b, TNF-α, Vcam1 and E-selectin, increased lymphatic vessel density and enhanced expression of Lyve-1 in the kidney further confirm that elevated level of circulating miR-505 leads to kidney inflammation in vivo." (PMID 35571179, 2022). "IL-1β is a potent proinflammatory cytokine that has previously been identified in glomerular macrophages in diseased MRL-lpr mice as well as Fcgr2b−/− mice, while elevated renal IL-1 family cytokine responses are common to several models of nephritis." (PMID 32541026, 2020). "Concerning pro-inflammatory cytokines, we found elevated levels of IL-1β, IL-6 and IL-8 in the serum of all patients, with or without nephritis, compared to the controls." (PMID 29190714, 2017). "The intrarenal expression of NLRP3, ASC, and caspase-1 suggests that they might be involved in the secretion of IL-1β and inflammation during anti-GBM nephritis." (PMID 22046355, 2011). "Our data suggest that IL-1β is not critical for nephritis progression but may in fact have a protective effect that is revealed when its function is inhibited in isolation (as opposed to full inflammasome complex targeting)." (PMID 37261358, 2023). "The gene expression levels of TNF-α, IL-1β, MCP-1, and IL-6, which are known as proinflammatory cytokines, were much higher in the WKY-HBSS rats than in WKY rats without nephritis." (PMID 23826305, 2013). "Furthermore, cleavage of pro-IL-1β into active IL-1β (p17) could not at all be detected in kidney isolates, excluding that other proteases induce IL-1β inside the kidney during heterologous anti-GBM nephritis." (PMID 22046355, 2011).